SLC39A4 (solute carrier family 39 member 4)
Diseases named in the same sentence as SLC39A4 in open-access papers (continued):
Sharing a sentence is not in itself a finding about the gene and the disease.
cancer (8 papers, 2017 to 2024). A tumor composed of atypical neoplastic, often pleomorphic cells that invade other tissues. "The analysis revealed that the mutation frequencies of SLC39A1, SLC39A4, and SLC39A8 in pan-cancer patients were 4%, 6%, and 0.9%, respectively." (PMID 38230214, 2024). "To investigate the associations between the expression of SLC39A1, SLC39A4, and SLC39A8 and immune infiltration in related cancers, we utilized the TIMER database." (PMID 38230214, 2024). "We have recently shown that ZIP4 (gene name SLC39A4), a zinc transporter, is functionally involved in cancer stem cell (CSC)-related cellular activities in HGSOC." (PMID 33316986, 2020). "SLC39A4 expression is also markedly higher in stage III-IV cancers than in stage I-II counterparts (Z = 2.97, P < 0.003), indicating that SLC39A4 expression is associated with NSCLC progression." (PMID 28775359, 2017). "Additionally, the mutation analysis indicated that mutations in the SLC39A4 gene have a significant and wide-ranging effect on DF, OS, and PFS in cancer patients, particularly in those with PAAD." (PMID 38230214, 2024). "However, genetic mutation of SLC39A4 had a significant impact on DFS and PFS in cancer patients (p-values: 2.718e-6 and 7.562e-4, respectively)." (PMID 38230214, 2024). "Notably, SLC39A4 was also identified as a potential immunomodulator in PAAD due to its strong correlation with immune cell infiltration in this cancer type." (PMID 38230214, 2024). "Moreover, silencing of SLC39A4 induced an epithelial-like phenotype, decreased cancer stem cell marker expression, and increased cisplatin sensitivity." (PMID 28775359, 2017). "However, although these findings indicate that SLC39A4 plays an important role in cancer cell migration and survival, the molecular mechanisms underlying these processes require further elucidation." (PMID 28775359, 2017). "Furthermore, we found that the gene SLC39A8 exhibited the lowest mutation frequency in KIRP, whereas mutations in SLC39A4 were found to significantly impact overall survival (OS), disease-free (DF), and progress-free survival (PFS) in cancer patients, particularly in those with PAAD." (PMID 38230214, 2024). "To gain further insights into the biological functions of SLC39A1, SLC39A4, and SLC39A8 in cancers, we utilized the LinkedOmics database to analyze their co-expression profiles in LIHC, CESC/PAAD, and KIRP, respectively." (PMID 38230214, 2024). "Nevertheless, the participation of SLC39A4 in EMT, stemness, and the chemotherapeutic resistance of cancer cells requires further research." (PMID 28775359, 2017). "In light of the aberrant expression and significant roles played by SLC39A1, SLC39A4, and SLC39A8 genes in specific cancers, as well as the link between genetic alterations and cancer development, we further investigated the genetic alterations of these genes using the cBioPortal database." (PMID 38230214, 2024). "SLC39A4, 7, 10, 11 and 14 in cancer tissues were significantly highly expressed compared with in normal tissues.(P<0.05) But, expression of SLC39A6 and SLC39A8 were higher in normal samples than in cancer samples." (PMID 33535184, 2021). "Additionally, immune infiltration analysis revealed that SLC39A1, SLC39A4, and SLC39A8 may function as immune regulators in cancers." (PMID 38230214, 2024).
tumor (7 papers, 2017 to 2025). "A meta-analysis of these studies revealed that increased tumour SLC39A4 expression was associated with shortened OS (Z = 2.05, P < 0.04) and DFS (Z = 2.46, P < 0.01)." (PMID 28775359, 2017). "Moreover, we also determined that SLC39A4 expression was associated with increased tumour volume (P = 0.0105), regional lymph node spread (P = 0.0030), and clinical stage (P = 0.0412)." (PMID 28775359, 2017). "Solute carrier family 39 member 4 (ZIP4) activates integrin α3 (ITGA3) by regulating the co-activation of ZEB1 and yes-associated protein 1 (YAP1) to promote EMT, tumor colonisation and organogenesis in vitro and vivo models of PC." (PMID 37550301, 2023). "Various tumor cells with high expression of SLC39A4 were found to be more resistant to the okadaic acid and are more sensitive to 8-chloroadenosine and allopurinol." (PMID 34925450, 2021). "We also observed an increase in SLC39A4 expression corresponding with the progression of in situ tumours to metastatic lesions." (PMID 28775359, 2017). "For this, the 90 tumour samples were dichotomized into groups with high or low SLC39A4 expression based on the median staining intensity observed in the array (μ = 6.516), and then evaluated for OS and DFS by Kaplan-Meier analysis." (PMID 28775359, 2017). "The clinical relevance of these results was confirmed with in vitro migration assays and a mouse model of tumour metastasis, indicating that SLC39A4 plays an important role in NSCLC cell migration." (PMID 28775359, 2017). "Similarly, the expression of SLC39A4 is significantly correlated with tumor size and overall survival in the “REACTOME ZINC TRANSPORTERS” pathway." (PMID 39411374, 2024).
metabolic disease (1 paper, 2023). A congenital disorder (due to inherited enzyme abnormality) or acquired (due to failure of a metabolically important organ) disorder resulting from an abnormal metabolic process. "ZIP4, also known as solute carrier family 39 member 4 (SLC39A4), has been shown to regulate concentrations of intracellular Zn2+, including in pancreatic cancer and metabolic diseases." (PMID 38072947, 2023).
SLC39A4 also shares sentences with these, for which no sentence is quoted: dermatitis (2 papers); hepatocellular carcinoma (2); lung squamous cell carcinoma (2); acne (1); adenocarcinoma (1); Anophthalmia (1); autosomal recessive disease (1); bladder urothelial carcinoma (1); breast invasive carcinoma (1); cervical squamous cell carcinoma (1); colon adenocarcinoma (1); endocervical adenocarcinoma (1); eosinophilia (1); Erythema (1); esophageal carcinoma (1); gastric adenocarcinoma (1); gastric cancer (1); genetic disease (1); glioma (1); head and neck squamous cell carcinoma (1); Hydrocephalus (1); Hypertension (1); infection (1); intervertebral disc degeneration (1); iron-deficiency (1); liver cancer (1); lung adenocarcinoma (1); lymphoma (1); neurological disease (1); organic acidemia (1).
A further 7 diseases each share a sentence with SLC39A4 in 1 paper.